DCN (decorin)
Diseases named in the same sentence as DCN in open-access papers (continued):
Sharing a sentence is not in itself a finding about the gene and the disease.
contact dermatitis (2 papers, 2015 to 2020). An inflammatory skin condition caused by direct contact between the skin and either an irritating substance or an allergen. "In a mouse model of contact dermatitis, decorin deficiency resulted in the reduced expression of chemokines, including KC/CXCL-1 and MCP-1/CCL2, and attenuated leukocyte recruitment." (PMID 25781946, 2015). "In relation to soft tissue repair, DCN has demonstrated roles in collagen fibrogenesis, modulating TGFβ, scar formation and inflammatory reactions during contact dermatitis." (PMID 32658899, 2020).
corneal dystrophies (2 papers, 2018 to 2024). "Although no shared rare variant was identified in the candidate corneal dystrophy gene DCN, given the greatly reduced levels of decorin immunoreactivity in the affected cornea we further examined this genomic region to assess if a variant was missed in our WGS analysis pipeline." (PMID 39169229, 2024).
cutis laxa (2 papers, 2012 to 2018). Cutis laxa (CL) is an inherited or acquired connective tissue disorder characterized by wrinkled, redundant and sagging inelastic skin associated with skeletal and developmental anomalies and, in some cases, with severe systemic involvement. "These proteins included several important ECM components, periostin (POSTN), elastin (ELN), and decorin (DCN); genetic mutations in these proteins are associated with different phenotypes of aging, such as cutis laxa and joint and dermal manifestations." (PMID 30574417, 2018). "ELN mutations resulting in autosomal-dominant cutis laxa are known to be associated with different phenotypes of aging (cutis laxa and cardiovascular and musculoskeletal abnormalities), and the DCN mutation leads to abnormal collagen fibril morphology and skin fragility." (PMID 30574417, 2018). "The influence of DS decorin on vimentin offers a novel explanation for the reported delay in wound healing of Dcn−/− mice and for the cutis laxa of EDS patients with defects in the biosynthesis of decorin." (PMID 23226541, 2012).
ductal carcinoma in situ (2 papers, 2014). "In ductal carcinoma in situ (DCIS) of the breast, both reduced stromal decorin expression and myxoid stroma are correlated with increased recurrence risk." (PMID 25593993, 2014).
endometrial carcinoma (2 papers, 2000 to 2021). A malignant tumor arising from the epithelium that lines the cavity of the uterine body. "Three genes (Decorin, TIMP3 and Cyclin D1) were identified to be differentially expressed between the benign endometrial tissue sample and the endometrial carcinoma samples (tissue and cell-lines)." (PMID 10901378, 2000).
Glucose intolerance (2 papers, 2019 to 2025). Glucose intolerance (GI) can be defined as dysglycemia that comprises both prediabetes and diabetes. "Taken together, our data show that loss of decorin causes glucose intolerance upon overfeeding, at least in part via changes in adipose tissue function." (PMID 30874564, 2019). "Loss of decorin associated with adipose genes involved in complement and coagulation cascades, as well as elevated adipose expression of Hal which has been implicated in inflammation and glucose intolerance through degradation of histidine." (PMID 30874564, 2019).
heart failure (2 papers, 2020 to 2021). Inability of the heart to pump blood at an adequate rate to meet tissue metabolic requirements. "For example, decorin and biglycan become highly expressed in models of hypertrophy and heart failure and are responsible for facilitating fibrillogenesis and fibrosis." (PMID 32805183, 2020).
joint disease (2 papers, 2008 to 2014). "Some of these decorin core protein species may therefore represent useful diagnostic biomarkers of joint disease." (PMID 18620607, 2008). "The dbpA of strain N40-D10/E9 conferred the weakest decorin- and GAG-binding activity, but the most robust joint colonization and was the only dbpA allele capable of conferring significant joint disease." (PMID 25079227, 2014).
Lyme disease (2 papers, 2008 to 2014). Lyme disease (named after the towns in the USA where the disease was first identified) is a bacterial infection caused by Borrelia burgdorferi. "The dbpA gene, which encodes a Lyme disease spirochete adhesin required for full infectivity, is allelic variable, and DbpA variants differ in their ability to promote spirochetal attachment to decorin, dermatan sulfate, or mammalian cells." (PMID 25079227, 2014).
lymphoma (2 papers, 2012 to 2021). A malignant (clonal) proliferation of B- lymphocytes or T- lymphocytes which involves the lymph nodes, bone marrow and/or extranodal sites.
osteoporosis (2 papers, 2020 to 2024). A condition of reduced bone mass, with decreased cortical thickness and a decrease in the number and size of the trabeculae of cancellous bone (but normal chemical composition), resulting in increased fracture incidence. "DCN has been widely shown to regulate cartilage degeneration, bone matrix in osteoporosis, tendon architecture, and functional activity." (PMID 39281413, 2024). "Additionally, the importance of decorin in cartilage biology was highlighted by the phenotype of decorin knockout mice, which showed that the depletion of decorin and biglycan induced progressive loss of bone mass, causing OA and an osteoporosis-like phenotype." (PMID 32353084, 2020).
papillary thyroid carcinoma (2 papers, 2019 to 2024). "In addition, we have reason to suspect that DCN have an important role in the carcinogenesis of papillary thyroid cancer." (PMID 31583243, 2019). "Furthermore, in papillary thyroid carcinoma, a group of iCAFs with a remarkable expression of CFD, DCN, or CCDC80, facilitated the migration of tumor cells through ECM degradation." (PMID 39003267, 2024).
periodontal disease (2 papers, 2008 to 2021). "ECM degradation is a key event in the early stages of periodontal disease, generating fragments that can act as danger-associated molecular patterns (DAMPs) such as fragmented aggrecan, fibronectin, biglycan, decorin and low molecular weight hyaluronic acid." (PMID 34255809, 2021). "The influence of LPS on the synthesis of matrix proteins, such as biglycan and decorin, therefore presents one, albeit significant, consequence of the pathogenic action of P. gingivalis in the progression of periodontal disease." (PMID 18471238, 2008). "Raised levels of decorin and biglycan in the gingival crevicular fluid (GCF) have been proposed as potential markers of alveolar bone destruction, during periodontal disease and peri-implantitis." (PMID 18471238, 2008).
polycystic ovary syndrome (2 papers, 2013 to 2021). A disorder that manifests as multiple cysts on the ovaries. "Endometrial hyperplasia is common among polycystic ovary syndrome (PCOS) patients, which display greater DCN protein expression in their proliferative phase of endometrial tissue." (PMID 34638928, 2021). "In the recurrence subnetworks, DCN, THBS1, and THBS2 are members of the signaling KEGG pathway, and FBN1 controls the bioactivity of TGFs and relates to polycystic ovary syndrome." (PMID 23555212, 2013).
posterior amorphous corneal dystrophy (2 papers, 2011 to 2022). Posterior amorphous corneal dystrophy (PACD) is a very rare form of stromal corneal dystrophy characterized by irregular amorphous sheet-like opacities in the posterior corneal stroma and in Descemet membrane and mildly impaired vision. "A human genome-wide linkage analysis of posterior amorphous corneal dystrophy identified a region of human chromosome 12 that is orthologous to a Mcs6 region that contains genes DCN, LUM, KERA, and EPYC." (PMID 21625632, 2011).
Pseudoexfoliation Syndrome (2 papers, 2018 to 2022). "The protein expression of decorin was also found to be increased in LECs of patients with PXG compared with those with pseudoexfoliation syndrome." (PMID 36611867, 2022). "Recent work has shown that decorin expression is conisderably upregulated in LECs during PCO and pseudoexfoliation glaucoma (PXG), in the aqueous humor of subjects in PDR, and in the vitreous humor of patients with rhegmatogenous retinal detachment and PVR." (PMID 36611867, 2022).
scleroderma (2 papers, 2018 to 2025). Scleroderma is a rare autoimmune connective tissue disorder characterized by abnormal hardening of the skin and, sometimes, other organs. "Meanwhile, this study primarily focused on the role of DCN in inhibiting TGF-β and alleviating fibrosis, without investigating the expression of DCN in fibroblasts of scleroderma patients." (PMID 40386129, 2025).
serous ovarian cancer (2 papers, 2010 to 2023). "This was illustrated in a recent re-analysis of two SNPs in the DCN gene that failed to achieve the minimal PTrend≤0.05 in stage 1 analysis, but conferred a small but significantly decreased risk of serous ovarian cancer in a combined analysis of data from two additional studies." (PMID 20628624, 2010). "Our discovery study was reasonably well powered, so the failure to find any associations with SNPs in genes involved in stromal epithelial cross-talk, except in DCN and TERT, suggests that genetic variation in this pathway is not a major determinant of serous ovarian cancer risk." (PMID 20628624, 2010).
Sjögren's syndrome (2 papers, 2022 to 2023). "Our study also found that decorin was significantly elevated in the salivary glands in the experimental Sjögren's syndrome model and pSS patients, and decorin induced the apoptosis of A253 cells and polarization of macrophages towards the M1 phenotype." (PMID 36033387, 2022). "In a primary Sjögren's syndrome mouse model (NOD.B10), decorin was found to induce TNF-α production and reduce MIP-1α and MCP-1 in the spleen via TLR4 rather than TLR2." (PMID 36033387, 2022).
stromal corneal dystrophies (2 papers, 2018 to 2023). "The corneal stroma, on the other hand, was found to be composed of classic keratocyte markers, keratocan (KERA), lumican (LUM), and decorin (DCN), all of which are associated with stromal corneal dystrophies." (PMID 37138096, 2023).
thyroid tumor (2 papers, 2016 to 2020). A benign or malignant neoplasm affecting the thyroid gland. "Moreover, lower decorin mRNA levels were also found in the follicular variant of PTC, therefore associating decorin loss with follicular-patterned thyroid tumours." (PMID 27025787, 2016). "Importantly, our novel protein expression data discovered by mass spectrometry and supported by immunoblot are consistent with a study that measured decorin mRNA abundance in thyroid tumours by quantitative polymerase chain reaction (qPCR)." (PMID 27025787, 2016).
Age-related cataract (1 paper, 2021). A type of cataract (opacification of the lens) that forms during the course of aging. "In age-related cataracts, DCN concentrations in human anterior aqueous humor and DCN expression in HLEC did not correlate with age, and opacity type or grade." (PMID 33918979, 2021).
aging (1 paper, 2021). A developmental process that is a deterioration and loss of function over time. "Thus, it is considered that degrading enzymes of biglycan and decorin can promote skin aging, and this study newly suggests possible roles of ADAMTS5 as a degrading enzyme of biglycan and decorin." (PMID 33573338, 2021).
Apert syndrome (1 paper, 2021). Apert syndrome (AS) is a frequent form of acrocephalosyndactyly, a group of inherited congenital malformation disorders, characterized by craniosynostosis, midface hypoplasia, and finger and toe anomalies and/or syndactyly.
B-cell non-Hodgkin lymphoma (1 paper, 2022). The most common type of non-Hodgkin lymphoma. "Interestingly, a subset of the members in the SLRP protein family have been previously identified in B-cell Non-Hodgkin’s lymphomas including DCN, BGN, ASPN, FMOD, LUM, PRELP, and TSKU." (PMID 36873459, 2022).
bladder urothelial cancer (1 paper, 2022). "The effect of decorin expression on survival in clinical patients was screened and analyzed using bladder urothelial carcinoma data from the Cancer Genome Atlas (TCGA) database." (PMID 35777025, 2022). "Analysis of TCGA data showed that decorin expression was significantly lower in bladder urothelial carcinoma samples than in normal tissues, while TGF-β1 expression did not change significantly." (PMID 35777025, 2022). "The expression levels of decorin in 408 people with bladder urothelial carcinoma were analyzed using TCGA data." (PMID 35777025, 2022). "We found that decorin was correlated with TGF-β1 expression in bladder urothelial cancer." (PMID 35777025, 2022).
bone metastasis (1 paper, 2025). Transfer of a neoplasm from its primary site to bones. "DCN expression was mainly found in fibroblast-like cells and in the matrix in the bone metastasis stroma and the current study suggests that reduced synthesis of DCN may contribute to the growth of the most aggressive bone metastases (Ki67 high, PSA low, MetB)." (PMID 40841830, 2025).
breast adenocarcinoma (1 paper, 2013). "Therefore, next we wanted to examine the effects of targeted decorin transduction on the behavior of human breast adenocarcinoma cells." (PMID 23007289, 2013). "In addition, by utilizing cultures of MCF7 human breast adenocarcinoma cells and a decorin producing adenoviral vector, we also examined whether targeted decorin delivery can modulate the behavior of these cells." (PMID 23007289, 2013). "Human breast adenocarcinoma cell line MCF7 and decorin producing adenoviral vector were applied for this purpose." (PMID 23007289, 2013). "By introducing a decorin producing adenoviral vector to the MCF7 human breast adenocarcinoma cells, we have also shown that decorin transduction in these decorin-negative cells results in marked changes in their behavior." (PMID 23007289, 2013). "Next, we examined whether by introducing decorin, a known antitumoral molecule, to widely used MCF7 human breast adenocarcinoma cells, we could modulate the behavior of these cells." (PMID 23007289, 2013).
Breast disease (1 paper, 2016). "Velleman and Clark (2015) hypothesized that higher levels of decorin production would lead to increased collagen crosslinking in Wooden Breast disease." (PMID 27097013, 2016).
Cachexia (1 paper, 2026). Severe weight loss, wasting of muscle, loss of appetite, and general debility related to a chronic disease. "As DCN binds to and directly inhibits myostatin, a potent inhibitor of muscle growth, it has been suggested as a potential target for maintaining the muscle mass in cachexia." (PMID 41392017, 2026).
cardiac amyloidosis (1 paper, 2025). Cardiac amyloidosis is a condition whereby cardiac tissue is infiltrated by amyloid fibrils. "Both decorin and HGF have previously been shown to provide diagnostic information in cardiac amyloidosis." (PMID 41141478, 2025).
carditis (1 paper, 2014). "Compared to dbpA alleles of B. afzelii strain VS461 or B. burgdorferi strain N40-D10/E9, dbpA of B. garinii strain PBr conferred the greatest decorin- and dermatan sulfate-binding activity, promoted the greatest colonization at the inoculation site and heart, and caused the most severe carditis." (PMID 25079227, 2014).
chondrodysplasia (1 paper, 2025). "Related to collagen structure is the complex formed between DCN and matrilin-1, a protein involved in matrix assembly, whose relative, matrilin-3, has been linked to certain chondrodysplasias." (PMID 40001470, 2025).
choroidal neovascularization (1 paper, 2021). An eye disorder described by the growth of new blood vessels that originate from the choroid through a break in the Bruch membrane into the sub–retinal pigment epithelium (sub-RPE) or subretinal space. "Interestingly, intravitreal injection of decorin in a choroidal neovascularization (CNV) mouse model was able to suppress TGF-β, VEGF, and TNFα upregulation." (PMID 34947953, 2021).
Cognitive impairment (1 paper, 2025). Abnormal cognition is characterized by deficits in thinking, reasoning, or remembering. "Together, these results demonstrate that suppression of DCN abolishes the protective effects of AKK against hippocampal damage and cognitive impairment in SAE, supporting a central role for DCN in mediating the neuroprotective mechanism of AKK." (PMID 41186245, 2025).
colitis (1 paper, 2022). Inflammation of the colon. "DCN deficiency significantly promotes EMT in a DCN−/− mice model of colitis-associated cancer." (PMID 36358747, 2022).
cyclopia (1 paper, 2020). "On the other hand, overexpressing Decorin at the one-cell stage caused cyclopia at 3 dpf." (PMID 32240230, 2020).
diverticulosis (1 paper, 2023). "In further exploration of the genetic basis of diverticulosis, research should delve into the genetic variations in extracellular matrix (ECM) components such as collagens, elastin, fibronectin, laminins, proteoglycans, tenascins, and decorin." (PMID 38004080, 2023).
dystocia (1 paper, 2012). Slow or difficult obstetric labor or childbirth. "Thus, the loss of both decorin alleles increases the risk of dystocia during labor despite the presence of both biglycan alleles." (PMID 22253749, 2012). "Thus, the biglycan/decorin double knockout mouse is a novel model of a genetic pathway for dystocia and delayed labor onset, which will be a useful model to test therapeutics and potentially decrease the rate of Cesarean births secondary to dystocia." (PMID 22253749, 2012).
endometrial tumors (1 paper, 2025). "In addition, PGs such as decorin and biglycan—both implicated in fibril formation and matrix organization of endometrial tumors—may also serve as future therapeutic targets or modulators of disease progression." (PMID 41228294, 2025).
esophageal cancer (1 paper, 2021). A primary or metastatic malignant neoplasm involving the esophagus. "Consistent with our previous report, the association of tumor invasiveness and the attenuated expression of DCN in the tumor-surrounding tissue were common findings in various cancers, including colon, lung, bladder, and esophageal cancers." (PMID 34884232, 2021).
Fibroadenoma (1 paper, 2014). A benign tumor of the breast characterized by the presence of stromal and epithelial elements. "Decorin was present at higher levels in fibroadenomas than in phyllodes tumors (P = 0.009, Mann-Whitney U test; n = 37, 35), whereas periostin was present at lower levels in fibroadenomas (P = 0.007, Mann-Whitney U test; n = 37, 35)." (PMID 25400079, 2014).
folate deficiency (1 paper, 2019). A nutritional condition produced by a deficiency of FOLIC ACID in the diet. "Thirdly, genes with an opposite expression pattern in folate deficiency and repletion cell lines: SORBS2, DCN, SLFN11, RUNX3, GALC, and HSPB7." (PMID 30836646, 2019).
frontotemporal dementia (1 paper, 2023). Frontotemporal dementia (FTD) comprises a group of neurodegenerative disorders, characterized by progressive changes in behavior, executive dysfunction and language impairment, as a result of degeneration of the medial prefrontal and frontoinsular cortices. "Decorin (DCN) and regulator of G protein signaling 1 (RGS1) were screened as diagnostic biomarkers in distinguishing AD from frontotemporal dementia and Huntingdon’s disease of AD." (PMID 37234685, 2023). "DCN and RGS1 associated with the immune response may be useful biomarkers for diagnosing AD and distinguishing the disease from frontotemporal dementia and Huntingdon’s disease." (PMID 37234685, 2023).